IFNAR1 (interferon alpha and beta receptor subunit 1)
Diseases named in the same sentence as IFNAR1 in open-access papers (continued):
Sharing a sentence is not in itself a finding about the gene and the disease.
infection (continued). "Following ECTV infection in the footpad, all Ifnar1-/-→ B6 and Ifnar1-/-→ Ifnar1-/- mice succumbed rapidly to the infection, whereas most B6→ Ifnar1-/- and B6→ B6 mice survived." (PMID 34015056, 2021). "To investigate the temporal effects of type I IFNs in HSV-2 genital disease, we used an antibody against IFNAR1 to block the receptor at different time points after infection." (PMID 34047696, 2021). "After challenge with ECTV, all Ifnar1-/-→ Rag1-/- mice quickly succumbed to infection whereas similar to Rag1-/- + B6 → Rag1-/-, most Rag1-/- + Ifnar1-/-→ Rag1-/- mice survived the infection with mild or no signs of disease." (PMID 34015056, 2021). "Here, we have used mixed BMCs where WT and Ifnar1-/- iMOs were exposed to the same environment during infection to show that IFNAR signaling in infected iMOs is essential to provide a positive feedback loop for IFN-I expression in vivo." (PMID 34015056, 2021). "We next evaluated the role for Sca2 in R. parkeri dissemination by measuring p.f.u. in spleens and livers following i.d. infection of Ifnar1-/-;Ifngr1-/- mice." (PMID 34423779, 2021). "In some cases, tails of DKO Ifnar1-/-;Ifngr1-/- or single mutant Ifngr1-/- mutant mice became inflamed after i.d. or i.v. infection." (PMID 34423779, 2021). "(d) Weight changes of Ifnar1-/-;Ifngr1-/- mice upon i.d. infection with 107 PFU of R. parkeri. n = 6 (WT) and 8 (sca2::Tn) individual mice." (PMID 34423779, 2021). "Again, Ifnar1-/- iBMDMs allowed for more robust bacterial replication than WT cells, as shown by increased bacterial fluorescence in these cells at 22 hours post-infection." (PMID 33684179, 2021). "Consistent with a previous study, knockout of IFNAR1 facilitated IAV‐luc infection and replication significantly." (PMID 33211371, 2021). "IFNAR1 blockade increases the proportion of TCF1+ CXCR5+ Tim-3− CD8+ T cells during LCMV Cl 13 infection." (PMID 34696381, 2021). "I.d. infection of Ifnar1-/-;Ifngr1-/- mice with R. parkeri elicits skin lesions that are grossly similar to human eschars." (PMID 34423779, 2021). "Our targeted LC-MS measurement for these metabolites showed that Ifnar1-/- BMDMs had lower stearoyl carnitine after infection, despite similar levels of free carnitine compared to wt." (PMID 34237114, 2021). "Our group has previously characterized the Ifnar1 −/− as a suitable murine model for USUV infection with severe disease." (PMID 34960621, 2021). "In contrast, CW3I514F infection of Ifnar1-/-Ifngr1-/- mice was highly attenuated, with only a ~100-fold increase in viral genomes in MLN and spleen compared to WT mice, and scant virus detected in the brain." (PMID 33705489, 2021). "Tnfa and Ifng responses, both of which tend to peak later in the infection, were similar in IfitL-/-Ifnar1-/- and Ifnar1-/- mice." (PMID 34591933, 2021). "By contrast, Irf3S1/S1Ifnar1-/- mice were permissive for infection and shed more virus in feces than Ifnar1-/- mice on days 7 and 14 p.i.." (PMID 34591933, 2021). "Our study demonstrates that eosinophils impact CD8+ T cell migration and proliferation during PbAAma1OVA-infection in Ifnar1-/- mice and thereby are contributing to the protection from ECM." (PMID 34659202, 2021). "Serum ALT elevations were comparable in the two types of mice at days 7 and 14 p.i., but HAV RNA levels in both liver and feces were significantly greater in the Ifnlr1-/-Ifnar1-/- mice than Ifnar1-/- mice on day 14 post-infection." (PMID 34591933, 2021). "(a) Survival of Ifnar1-/-;Ifngr1-/- mice upon i.v. infection with 5 × 106 PFU of R. parkeri. n = 7 (WT), 10 (sca2::Tn), and 7 (MC1_RS08740::Tn R. parkeri) individual mice." (PMID 34423779, 2021). "Together, the gross pathological analysis and fluorescence-based assay suggest that Sca2 likely does not significantly enhance R. parkeri spread throughout the skin during i.d. infection of Ifnar1-/-;Ifngr1-/- mice." (PMID 34423779, 2021).
infection (continued). "The observed shift in cell frequencies resulted in a changed CD4+/CD8+ T cell ratio in the spleen, which was significantly lower in Ifnar1-/- mice than in WT controls after PbAAma1OVA infection." (PMID 34659202, 2021). "We also found that compared to B6→ B6 and B6→ Ifnar1-/- mice, the viral loads in Ifnar1-/-→ B6 and Ifnar1-/-→ Ifnar1-/- mice were increased 10-fold at 5 days post-infection (dpi) in the spleen and 100-fold in the liver and the spleen at 7 dpi." (PMID 34015056, 2021). "We observed skin lesion formation at all infectious doses, from 107 to 10 bacteria, suggesting that i.d. infection of Ifnar1-/-;Ifngr1-/- mice elicits lesions with doses similar to what is delivered by tick infestation." (PMID 34423779, 2021). "We infected WT and Ifnar1-/-Ifngr1-/- mice, due to mouse availability, with CW3 or CW3I514F, and found that while CW3 infection led to dramatic weight loss of Ifnar1-/-Ifngr1-/- mice by 3 dpi, CW3I514F did not cause the same rapid morbidity." (PMID 33705489, 2021). "Genes encoding interferons (Ifnb, Ifnl2 and Ifnl3), chemokines (Ccl7, Ccl5, and Cxcl10), and ISGs (Ifit1, Ifit2, Ifit3b, Oas3, Ifi44, Rsad2, and Isg15, among others) were prominently represented among those induced by infection in Ifnar1-/- mice." (PMID 34591933, 2021). "Type I IFNs are induced early upon Plasmodium infection and Ifnar1-/- mice have been described to be at least partially protected from ECM upon infection with wild type (WT) or transgenic P. berghei ANKA parasites." (PMID 34659202, 2021). "Strikingly, when comparing gene sets in Irf9-/- or Ifnar1-/- with wt after infection, we identified OXPHOS and FA metabolism gene enrichment in Irf9-/- and Ifnar1-/-." (PMID 34237114, 2021). "These included 47 genes that were significantly induced by infection in both Irf3S1/S1Ifnar1-/- and Ifnar1-/- mice, and 322 induced only in Ifnar1-/- animals." (PMID 34591933, 2021). "Both, eosinophil-depleted and isotype treated Ifnar1-/- mice had higher levels of CCL5 in the spleens during PbA infection compared to the infected WT controls." (PMID 34659202, 2021). "Mice were treated with anti‐IFNAR1 or isotype control antibodies (500 μg i.p.)every other day, starting from the day before infection, up to day 5 post‐infection." (PMID 34547174, 2021). "The drop in glutaminolysis-dependent OCR was slightly more pronounced in Ifnar1-/- compared to wt BMDMs after infection." (PMID 34237114, 2021). "After conditioning for sex, a total of 1028 genes were significantly upregulated, and 74 down-regulated, by infection in Ifnar1-/- mice." (PMID 34591933, 2021). "There was an increase in the CCL5+ CD8+ T cell count (p=0.002) in Ifnar1-/- mice upon PbA-infection." (PMID 34659202, 2021). "ZIKV genome quantified with RT-qPCR of RNA isolated from maternal spleen and brain tissue showed patterns of X1 and WT infection similar to those seen in adult Ifnar1−/− mice." (PMID 33080971, 2020). "In order to determine the protective efficacy of this hAd5-ZKV, we used a Ifnar1-/- lethal infection model that has been used to validate several ZIKV vaccines currently in phase I trials." (PMID 32272595, 2020). "Further characterization revealed that Irf3−/− mice, but not Irf7−/− mice, showed a similar early increase in liver parasite burden as Ifnar1−/− mice following P. yoelii (Py17XNL) infection." (PMID 33408718, 2020). "The NB results also confirmed that FCV 2280 infection led to the decrease of IFNAR1 mRNA in a virus dose-dependent manner." (PMID 33075108, 2020). "To address the role of IFNAR signaling specifically in T cells during in vivo infection, we transferred CD4+ cells from Ifnar1-/- or C57BL/6 WT mice to Rag1-deficient mice (Rag1-/- mice)." (PMID 32210480, 2020). "We performed an RNA-seq assay on the FCV strain 2280 infection at 12 hpi and found that infection led to the downregulated expression of interferon receptor 1 (IFNAR1), suggesting that FCV 2280 is able to evade the host antiviral response." (PMID 33075108, 2020).
infection (continued). "To this end, we performed a kinetics analysis to monitor the infection and Th1 subset in infected mice with IFNAR deficiency (Ifnar1-/-) and control 129/SvEv WT mice." (PMID 32210480, 2020). "Secreted type I interferon functions by interacting with the IFNARs on the cell surface, but FCV 2280 infection blocks the activation of this signalling pathway by decreasing the expression level of IFNAR1." (PMID 33075108, 2020). "Compared to infection with the parental virus, rFCV 2280-F9 p30 infection displayed attenuated activities in reducing the level of IFNAR1 and inhibiting the phosphorylation of STAT1 and STAT2, whereas rFCV F9-2280 p30 displayed enhanced activities." (PMID 33075108, 2020). "Strikingly, Ifnar1−/− mice exhibited significantly reduced parasite burdens in the liver and spleen over the course of infection compared with WT mice." (PMID 32101732, 2020). "In one study showing inhibition of DC and T cell activation by IFN-I signaling, Ifnar1−/− mice or multiple injections of anti-IFNAR antibodies were used, which is different from infection of wild type mice." (PMID 33344264, 2020). "In conclusion, we have shown that FCV 2280 infection blocks the JAK-STAT pathway by promoting the degradation of IFNAR1 mRNA." (PMID 33075108, 2020). "The levels of IFNAR1 mRNA were still reduced with Act.D treatment upon FCV 2280 infection, suggesting that the decreased IFNAR1 mRNA levels in FCV-infected cells were a result of enhanced mRNA degradation." (PMID 33075108, 2020). "By contrast, basal IFNAR1 signaling is still required for Zn mobilization during fungal challenge, which reflects a paradoxical dichotomy IFNs-I can exhibit in certain infection settings." (PMID 32428860, 2020). "To explore the mechanism by which FCV 2280 downregulates the expression of IFNAR1, we first analysed the level of IFNAR1 mRNA upon 2280 infection using qRT-PCR and Northern blotting (NB)." (PMID 33075108, 2020). "Overall, X1 ZIKV is able to replicate the infection kinetics of WT ZIKV in the spleens of Ifnar1−/− mice but exhibits tissue-specific restriction in viral growth in brain tissue." (PMID 33080971, 2020). "After day 29 post primary infection, the Ifnar1-/- mice received a second hACE2 or GFP mRNA transfection, followed 24 hours later by a boost with 5x104 FFU per mouse of SARS-CoV-2, administered both IV and IN route." (PMID 33326500, 2020). "Consistent with results in WT mice, CHK-265 reduced viremia in Rag1-/- and Ifnar1-/- mice for the first 24 hours post-infection (hpi), and by 48 hpi, both Rag1-/- and Ifnar1-/- mice had high viremia comparable to that in isotype mAb-treated mice." (PMID 32760128, 2020). "The molecular mechanism by which this occurs is that FCV 2280 infection blocks the JAK-STAT pathway through promoting the degradation of IFNAR1 mRNA by FCV p30 protein." (PMID 33075108, 2020). "In contrast, testes of IFNAR1-blocking antibody treated-MMP9-/- mice harbored a significantly lower viral load than those of treated WT mice at 10 days post infection (dpi)." (PMID 32302362, 2020). "In this study, 2 mg of MAR1‐5A3 anti‐IFNAR1 antibody was administered into immunocompetent WT animals on the same day as infection." (PMID 32346479, 2020). "We observed a significant increased level of mRNA expression of Ifnb1 and Ifnar1 in the lung and spleen tissue at both 21 and 84 days after infection in comparison with uninfected PBS control mice." (PMID 31801478, 2019). "Virus spread in Ifnar1−/− mice was accompanied by significantly higher viral RNA levels at day 4 post infection, and it is conceivable that the cytopathic effects of ZIKV contributed to the faster onset of disease in Ifnar1−/− mice compared with WT mice." (PMID 31511023, 2019). "Surprisingly, DENV1B still has higher infection efficiency than DENV1E in IFNAR1-/- MEFs, just like what it does in wild type MEFs." (PMID 30830907, 2019).
infection (continued). "In line with the IFNAR1-dependent increase of systemic ornithine levels upon infection, these data indicate that IFNAR1 represses the degradation of ornithine via OTC in hepatocytes." (PMID 31784108, 2019). "We investigated the spatial distribution of ZIKV RNA in the CNS of mice by in situ hybridization (ISH) at peak disease, i.e., day 6 for WT, day 4 for Ifnar1−/−, and day 8 post infection for Rag1−/− mice." (PMID 31511023, 2019). "Immunoprecipitation of IFNAR1 in WT BMDMs indicated RIPK1 associates with IFNAR1 following Type I IFN stimulation, while in vivo infection of Ripk3−/− mice induced similar cytotoxicity to Ifnar1−/− mice." (PMID 31402916, 2019). "Since it was apparent that type I IFNs played an important role in inhibiting the replication of ZIKV, we conducted in vitro infection experiments in wild-type or type I IFN receptor chain 1 (IFNAR1) knock-out mouse embryonal fibroblasts (MEFs)." (PMID 31673117, 2019). "While this indicates that sustained early TNF and CXCL1 are not due to increased bacterial burden at this timepoint, there have been reports of increased or decreased bacterial load in Ifnar1-/- mice in longer term infection models." (PMID 31385572, 2019). "We functionally tested the role of type I IFNs by generating CD169−/−Ifnar1−/− mice and found that the infection levels in their spleens were still significantly elevated (5-fold) compared with the control Ifnar1−/− mice." (PMID 30595553, 2019). "Whereas earlier studies demonstrated 100% survival of mice infected with Δess, only 38% of Ifnar1−/− mice survived infection with Δess." (PMID 31801066, 2019). "In summary, our data indicate that hepatocyte-intrinsic IFNAR1 signaling acts as a transcriptional regulator of liver metabolism and results in changes of circulating metabolites during infection." (PMID 31784108, 2019). "The observed infection-dependent reduction of the urea cycle end product 13C5 arginine further supported the notion of an IFNAR1-mediated break of the urea cycle." (PMID 31784108, 2019). "Together these findings raise the possibility that IFN-1/IFNAR1 signaling exerts beneficial effects in early stages of infection when innate immune responses dominate." (PMID 31417551, 2019). "Viral RNA levels were approximately 50–100-fold higher in IFNAR1 KO cells compared to those seen in wild-type cells, indicating an important role of type I IFNs in restricting the infection in cell culture." (PMID 31673117, 2019). "The Ifnar1-/- mice received the CD4+T cell depleting antibody three days prior to infection and a second dose on the day of subcutaneous (SC) infection with 1x105 focus forming units (FFU) of ZIKV." (PMID 30212537, 2018). "IFNαR-dependent signals also impaired myeloid progenitor cell activity in the BM during infection, and significantly enhanced monocyte differentiation was observed in cultured Lin- cells from Ifnar1-/- mice, relative to wild type mice." (PMID 30080899, 2018). "Seven days after infection, the CD4+T cell-depleted Ifnar1-/- mice showed a significant difference in weight that was maintained until day eleven post infection, when the CD4 depleted mice began to succumb to infection." (PMID 30212537, 2018). "Control of infection by acute MNoV strains (e.g., CW3, MNV-1) depends upon the presence of intact type I IFN signaling, as Ifnar1−/− and Stat1−/− mice succumb to lethal infection." (PMID 29361691, 2018). "We noted a significant difference in the mortality between the CD4 depleted and control mice, where 60 percent of the depleted mice succumb to the infection compared to 100 percent survival of the control Ifnar1-/- animals." (PMID 30212537, 2018). "HSCs are typically in G0, though HSC quiescence was reduced in Ifnar1-/- mice at both steady state and upon infection indicating that HSCs proliferated more in Ifnar1-/- mice whereas WT HSCs remained quiescent." (PMID 30080899, 2018).
infection (continued). "When in the same microenvironment, WT and Ifnar1-/- HSPCs and HSCs showed similar cycling at both steady state and during infection." (PMID 30080899, 2018). "A previous study indicated that type I IFN receptor-signaling in another EV-A71-permissive RD cell line was impaired during EV-A71 infection because EV-A71 2A targeted the IFNAR1 protein for degradation." (PMID 30563052, 2018). "One study demonstrates that EV-A71 2A reduces the IFNAR1 protein level during EV-A71 infection, leading to the downregulation of IFNAR signaling to ISG induction." (PMID 30563052, 2018). "In whole BM we found similar expression of RIPK3 and MLKL in WT and Ifnar1-/- mice during IOE infection." (PMID 30080899, 2018). "While infection mediated a decline in Ifnar1 mRNA relative to basal levels in microglia by day 5 p.i., it did not alter expression levels in astrocytes." (PMID 29491163, 2018). "IOE infection induces BM hypocelluarity with a profound decrease in cellularity on day 8 post-infection, which is mitigated by Ifnar1 deletion." (PMID 30080899, 2018). "WT C57BL/6 female mice were administered anti-Ifnar1 Ab 1 day before infection with DENV2, as DENV cannot inhibit type I interferon production and signaling in mouse cells, unlike in human cells." (PMID 30072692, 2018). "Within the HSPC compartment of IOE-infected chimeric mice we observed an increase in Ifnar1-/- cells relative to WT counterparts, indicating that HSPCs are directly impaired by IFNα/β during infection." (PMID 30080899, 2018). "We therefore challenged C57BL/6 WT and IFNAR1−/− mice, which had healed a primary subcutaneous infection with L. major, by injection of the same parasite inoculum into the contralateral footpad." (PMID 29459858, 2018). "By contrast, the quantities of type I IFNs generated in BALB/c mice infected with L. major were not sufficient to impair the immune response as revealed by the unaltered course of infection in BALB/c IFNAR1−/− mice." (PMID 29459858, 2018). "We treated HIV-1-infected humanized mice with the anti-IFNAR1 mAb from week 6 through week 10 after infection." (PMID 29304123, 2018). "We did not expect to see such high viral titers in both the periphery and the CNS day eight post infection in the control Ifnar1-/- mice." (PMID 30212537, 2018). "The mRNA of the immediate early cytokine Tnf was induced upon infection in both WT and Ifnar1-/- mice although the levels were lower in Ifnar1-/- when compared to WT animals." (PMID 29112952, 2017). "The progression of syncytia formation during NBV infection was also evaluated by immunofluorescence microscopy through the detection of NBV σ proteins in Ifnar1 knockdown cells." (PMID 28806913, 2017). "To assess the effect of type I IFN signaling on susceptibility to S. typhimurium infection after streptomycin treatment, we initially investigated the survival of WT and Ifnar1-/- animals after infection with various doses of S. typhimurium." (PMID 29190678, 2017). "ZIKV RNA measurements on day 6 post infection in the brain, ovary, spleen and liver of Stat2-/- and Ifnar1-/- mice showed the highest viral RNA levels in the brain, followed by ovary, spleen and minimum levels in the liver." (PMID 28278235, 2017). "IFNAR1 is crucial in engaging innate cell machinery to restrict viral spread, and in expanding sufficient leukocyte numbers to tackle intracellular infection." (PMID 28769107, 2017). "Markedly more infected cells were apparent when STAT1 or IFNAR1 were knocked down, while the control NS cells were resistant to infection similar to unmodified P. leucopus cells." (PMID 28650973, 2017). "Flow cytometry analysis revealed comparable numbers of alveolar macrophages (4% CD11chighSiglecF+ alveolar macrophages of CD45+ leukocytes) in lungs of Ifnar1-/- and WT animals 12 h after infection with K. pneumoniae." (PMID 29112952, 2017).